TUFM (Tu translation elongation factor, mitochondrial)
Diseases named in the same sentence as TUFM in open-access papers (continued):
Sharing a sentence is not in itself a finding about the gene and the disease.
ovarian cancer (1 paper, 2023). A primary or metastatic malignant neoplasm involving the ovary. "This correlation was not clear with the ovarian cancer cell lines with low-OXPHOS subunit expression; specifically, the OVCAR-8 cells had normal levels and, in some cases, higher levels of PGC1α, TFAM, TUFM, and DARS2 protein expression." (PMID 36937395, 2023).
periodontitis (1 paper, 2025). An acute or chronic inflammatory process that affects the tissues that surround and support the teeth. "Although we identified the therapeutic mechanism of DMF in periodontitis and revealed a novel role for TUFM in macrophage polarization via mitophagy, this study had some limitations." (PMID 40246816, 2025). "Staining showed that intracellular TUFM levels were significantly inhibited in periodontal tissues of the mouse model of periodontitis." (PMID 40246816, 2025). "Our results demonstrate for the first time that DMF protects mitochondrial function and inhibits oxidative stress through TUFM-mediated mitophagy in macrophages, resulting in a shift in the balance of macrophage polarization, thereby attenuating periodontitis." (PMID 40246816, 2025). "We found, for the first time, that adding Pg.LPS/IFN-γ resulted in a significant decrease in the intracellular TUFM level in macrophages, which had similar results in the mouse periodontitis model, indicating that the decrease of TUFM is an important mechanism in periodontitis development." (PMID 40246816, 2025). "Moreover, when macrophages were activated with Pg.LPS/IFN-γ, intracellular TUFM decreased significantly, while using DMF reversed the decrease in TUFM level, implying that the decreased TUFM level may be a mechanism for periodontitis pathogenesis." (PMID 40246816, 2025). "Second, the beneficial effects of DMF on periodontitis via TUFM were demonstrated only in vitro using siRNA or not TUFM-knockout mice." (PMID 40246816, 2025).
prostate carcinoma (1 paper, 2021). A carcinoma that arises from epithelial cells of the prostate gland. "TUFM and ACPP, which are frequently associated with prostate cancer, and two metabolic enzymes, LDHB and OXCT1, were further confirmed at the protein level in DHT (androgen)- and FSK (PKA signaling)-stimulated VCaP cells by immunoblotting." (PMID 34680521, 2021). "In addition, TUFM is upregulated at the protein level in prostate cancer, and ACPP has been used as a diagnostic and prognostic marker together with prostate-specific antigen (PSA) for prostate cancer." (PMID 34680521, 2021). "In addition, the expression levels of three proteins—TUFM, and HNRNPH3 from the DHT-specific proteome, and CCT2 from the FSK-specific proteome—were related to the progression-free interval in prostate cancer patients." (PMID 34680521, 2021).
pulmonary arterial hypertension (1 paper, 2022). Pulmonary arterial hypertension (PAH) is a group of diseases characterized by mean pulmonary artery pressure >20 mmHg and elevated pulmonary arterial resistance leading to right heart failure. "Moreover, the most recent study has provided us with pulmonary arterial hypertension-related mitochondrial proteome analysis of the rat model, which the differential expression of TUFM was identified." (PMID 35936222, 2022).
respiratory failure (1 paper, 2018). The significant impairment of gas exchange within the lungs resulting in hypoxia, hypercarbia, or both, to the extent that organ tissue perfusion is severely compromised. "Mutations in TUFM have previously been shown to cause combined oxidative phosphorylation deficiency 4, a syndrome consisting of intrauterine growth retardation, developmental regression, hypotonia and respiratory failure." (PMID 29691431, 2018).
infection (8 papers, 2017 to 2025). The state of being infected such as from the introduction of a foreign agent such as serum, vaccine, antigenic substance or organism. "As TUFM is implicated in mitophagy activation upon infection by certain RNA viruses, we postulated that TUFM-KD leads to excessive accumulation of dysregulated mitochondria and thereby potentiates apoptosis in vIRF-1-deficient cells." (PMID 34511600, 2022). "In the early stage of infection, the viral Gn protein interacts with Tu Translation Elongation Factor, Mitochondrial (TUFM), and LC3B to induce mitophagy." (PMID 35269494, 2022). "Additionally, positive interactors of DCAF11 that were lost upon infection encompass splicing factors THRAP3 and SRSF5, the microtubule-associated protein MAP4, mitochondrial ribosomal protein MRPL12, and the TUFM mitochondrial translation elongation factor." (PMID 39383947, 2024). "Mitochondrial translation elongation factor Tu (TUFM) is a mitochondrial protein encoded by the nuclear genome that potently inhibits RLR (RIG-I-like receptors) signaling and promotes autophagy during a pathogen infection, particularly viruses." (PMID 38370576, 2023). "Compared with that of WT mice at 3 days post-infection (dpi), LC3-II expression was lower, but IFNβ mRNA level was higher in the lungs of the TUFM-KD mice." (PMID 37909764, 2023). "Using TUFM (Tu translation elongation factor, mitochondrial) and calnexin as markers for mitochondria and ER, respectively, we observed that EV-A71 infection did not alter the overall distribution of cellular organelle at 4 hpi or 8 hpi." (PMID 40522993, 2025).
cancer (7 papers, 2017 to 2025). A tumor composed of atypical neoplastic, often pleomorphic cells that invade other tissues. "In addition, TUFM depletion promoted caspase-8 activation induced by treatment with TNF-related apoptosis-inducing ligand in cancer cells, potentially via dysregulation of mitochondrial dynamics and mitophagy." (PMID 34511600, 2022). "Upregulation of TUFM has been reported in lung, esophageal, gastric, liver, and pancreatic cancers." (PMID 28449687, 2017). "Machine learning models based on seven LM-related genes (CHEK2, LIPT1, TUFM, NDUFA10, AGK, PNPLA2, and GFM1) accurately predicted immunotherapy outcomes for multiple cancer types, including LUSC, and outperformed other currently known biomarkers." (PMID 40568577, 2025). "To investigate molecular mechanisms of the BEX2-mediated maintenance of dormant cancer stem cells, we screened for BEX2-binding proteins and identified TUFM, which is a translation elongation factor of tRNA19." (PMID 33299012, 2020).
tumor (4 papers, 2017 to 2025). "In addition to the dramatic changes observed in ACADL associated with tumor invasiveness, we also identified another protein involved in the mitochondrial translation machinery, i.e., TUFM." (PMID 37297007, 2023).
infectious disease (1 paper, 2024). A disorder directly resulting from the presence and activity of a microbial, viral, or parasitic agent in humans. "TUFM plays a role in the regulation of autophagy and innate immunity and is associated with infectious disease and SARS-CoV-2 infection." (PMID 38181733, 2024).
mitochondrial disease (1 paper, 2025). "Pathogenic variants in any of the four nuclear genes encoding the mitochondrial elongation factors EFG1, EFG2, TUFM, and TSFM have been implicated in causing severe mitochondrial disease." (PMID 39827178, 2025).
TUFM also shares sentences with these, for which no sentence is quoted: asthma (2 papers); cholangiocarcinoma (2); Infantile encephalopathy (2); inflammatory bowel disease (2); autoimmune disease (1); Brody myopathy (1); colorectal tumors (1); common variable immunodeficiency 3 (1); COVID-19 (1); diabetes (1); dilated cardiomyopathy (1); dysplasia (1); endometriosis (1); gastric cancer (1); Hepatic steatosis (1); immunodeficiency 52 (1); leukodystrophy (1); Leukoencephalopathy (1); lung adenocarcinoma (1); microcephaly (1); multiple sclerosis (1); Niemann-Pick disease (1); non-alcoholic fatty liver disease (1); nonalcoholic steatohepatitis (1); OXPHOS disease (1); pancreatic adenocarcinoma (1); Parkinson disease (1); pulmonary hypertension (1); tubulovillous adenoma (1); type 2 diabetes (1).
A further 1 disease shares a sentence with TUFM in 1 paper.